U6 (U6 spliceosomal RNA )
Synonyms: LOC124900632
Gene: Small nuclear RNA gene on chromosome 15 (21,428,879 to 21,428,985, reverse strand). Ensembl gene ENSG00000275174.
Gene Ontology:
Molecular function: U4 snRNA binding
Biological process: formation of quadruple SL/U4/U5/U6 snRNP; spliceosomal tri-snRNP complex assembly
Cellular component: U4/U6 x U5 tri-snRNP complex; U6 snRNP
Homologues: Orthologues: macaque U6 (92% identical), macaque U6 (90% identical), guinea pig U6 (79% identical), dog U6 (76% identical), pig U6 (68% identical). Paralogues in human: RNU6-631P (100% identical), RNU6-749P (100% identical), U6 (100% identical), RNU6-1021P (99% identical), RNU6-286P (98% identical), U6 (98% identical), RNU6-127P (93% identical), RNU6-1239P (93% identical), RNU6-1268P (93% identical), RNU6-473P (93% identical), RNU6-617P (93% identical), RNU6-816P (93% identical), and 1289 more.